MIR5705 (microRNA 5705)
Synonyms: hsa-mir-5705
Gene: MicroRNA gene on chromosome 4 (87,300,495 to 87,300,583, reverse strand). Ensembl gene ENSG00000263981.
Homologues: Orthologues: chimpanzee MIR5705 (100% identical).